CD69 (CD69 molecule)
Diseases named in the same sentence as CD69 in open-access papers (continued):
Sharing a sentence is not in itself a finding about the gene and the disease.
tumor (continued). "We observed an increase of CD103+ CD69+ CD8+ T cells in the tumor stroma of disease-free patients compared with metastatic patients and healthy control skin (CS)." (PMID 33240271, 2020). "Tumor-infiltrating MAIT cells highly expressed CD69, CD103, CD38, and CD39 with lower expression of CD27 and CD49d compared with peripheral MAIT cells." (PMID 33205061, 2020). "In the recent report, FoxP3 expression in tumor-infiltrating CD4+ T cells is observed to overlap with the CD69 expression, suggesting that tumor-infiltrating Treg cells are a tissue-resident population." (PMID 33379384, 2020). "It is also important to note that some reports of increased expression of activation markers by tumor-derived MAIT cells relied on CD69 as measure of activation." (PMID 32508830, 2020). "The ability of MIL-38-CD3 to activate T cells was assessed using in vitro co-culture assays with tumour cell lines of varying GPC-1 expression by measurement of CD69 and CD25 expression, before cytolytic activity was assessed in a similar co-culture." (PMID 33302918, 2020). "In NK cells, CFP upregulated CD69 expression and cytotoxic mediator secretion, which is a phenomenon that inhibited CT-26 tumor cell infiltration in the lungs." (PMID 33302530, 2020). "For example, the Th cells and the Tcyt cells in tumour tissue expressed the activation markers CD69 less often, and more often expressed the inhibitor PD-1, than those in adjacent normal tissue." (PMID 33228141, 2020). "Consistent with a requirement for T-cell responses in the observed tumor suppressive effects by anti-PD-L1 blockade, both activated CD69+/CD8+ and IFNγ+/CD8+ T cells correlated with changes in survival in the different treatment groups." (PMID 32075966, 2020). "Tumour stage was also weakly correlated to the fraction of NK cells expressing CD69 (p = 0.025), with an increased fraction found in tumours of higher stages." (PMID 33228141, 2020). "In our hands, pDCs activate both Vδ2+ and Vδ2- T cells, provoke major phenotypic changes (upregulation of CD25 and CD69, modulation of immune checkpoint expression) and drive their cytotoxicity toward tumor cells." (PMID 32435249, 2020). "These tissue-resident lymphocytes within the liver and tumor have unique characteristics in terms of their functions, phenotypes, and transcriptional properties, compared to the circulating or CD69 lymphocytes." (PMID 33379384, 2020). "NK cells (CD56+/CD16+) were found to be significantly enriched in tumours compared to adjacent normal tissues, and to express CD69 and NKG2D less often." (PMID 33228141, 2020). "When paired values were compared, there was significant change in means between sentinel node and primary tumour CD69+ activation (p = 0.0314)." (PMID 33339891, 2020). "We reported that intratumoral NKT cells expressing lower CD69 and higher CD62L as compared to splenic NKT cells suggesting that tumor-associated NKT cells display memory phenotype." (PMID 31387637, 2019). "Peripheral and tumor-associated NK cells from STAT3-targeted tumor-bearing mice expressed elevated levels of NK activation markers NKG2D, CD69, Fas ligand (FasL) granzyme B, perforin, and IFNγ, resulting in reduced tumor growth and enhanced survival." (PMID 31057536, 2019). "Peripheral and tumor-associated NK cells in STAT3-targeted tumor-bearing mice, exhibit higher expression of the NK activation markers NKG2D, CD69, Fas ligand (FasL), granzyme B, perforin, and IFNγ, resulting in reduced tumor growth and enhanced survival." (PMID 31057536, 2019). "All TRuCs and CARs in Jurkat cells were functional, since co-culture with CD19-expressing tumor cells led to upregulation of CD69 in the transduced Jurkat cells." (PMID 31064990, 2019). "Peripheral and tumor-infiltrating NK cells were analyzed for Tim-3, Annexin V, CD69, CD107a and IFN-γ expression by flow cytometry." (PMID 31109341, 2019).
tumor (continued). "Instead, L-selectin expression promotes early T cell activation as measured by CD69 expression inside the tumor, spleen and involved LN." (PMID 31249570, 2019). "As brachial LN is not a site of tumor antigen presentation, this finding suggests a role for the host conditioning regime in upregulating CD69 on F5LΔP T cells and F5LselKO T cells as found in the spleens of non-tumor bearing mice." (PMID 31249570, 2019). "Both splenic and tumor-infiltrating T cells upregulated expression of the early activation marker CD69 in response to poly(I:C)c, whereas PD-1 expression was unaffected." (PMID 31694706, 2019). "Tumor cells were dynamically surveyed by CD69+ CD103+ CD8+ TRM cells, and TRM cell responses were observed more often and at higher densities in peritumoral skin than in the skin of tumor‐bearing mice." (PMID 31230406, 2019). "The blockade of TIGIT via mAbs reversed the exhaustion of anti-tumor NK cells in multiple tumor models, enhanced the infiltration of activated (CD69+) NK cells into tumors and thereafter improved the OS of the host." (PMID 30805309, 2019). "Rather, the higher levels of CD69 on L-selectin sufficient T cells in the spleens of tumor-bearing mice are a direct consequence of tumor load." (PMID 31249570, 2019). "Analysis of splenic and tumor-resident B and NK cells showed a slight increase in splenic B cell numbers; both cell populations upregulated CD69 expression upon therapy." (PMID 31694706, 2019). "Recently, CD69 has been indicated in the induction of T cell exhaustion in a breast cancer tumor model in mice, where anti-CD69 antibody treatment was proven to enhance anti-tumor activity, pointing CD69 as a novel target for cancer immunotherapy." (PMID 31649887, 2019). "Addition of PDL1 (CD274) to the gene signature interrogated, drastically reduced the benefit of a higher infiltration in the tumor of CD8+CD69+ cells." (PMID 31214178, 2019). "The residual population of tumor-infiltrating CD4+ T-cells exhibited reduced expression of the early activation marker CD69." (PMID 31188899, 2019). "CD8 T cell populations in PR patients show enhanced frequencies of T effector memory re-expressing CD45RA (TEMRA) cells, as well as T cells that express markers of terminal differentiation (CD95+) and egression from tumor tissue (CD69-)." (PMID 31176366, 2019). "CD69 expression was upregulated on L-selectin sufficient (F5LΔP) T cells harvested from tumor tissues 18 h following transfer to tumor-bearing mice whereas CD69 on L-selectin deficient T cells (F5Lselko) was not increased." (PMID 31249570, 2019). "At the tumor site, treatment decreased MDSCs and Treg, and increased the number of CD69+CTL and effector CD4+ cells." (PMID 31214178, 2019). "In non-tumor bearing animals which had been irradiated and vaccinated with peptide, CD69 was equally upregulated on F5LΔP cells and F5 L-selectin knockout T cells in the spleen." (PMID 31249570, 2019). "We show that IL-33 recruits eosinophils indirectly, via stimulation of tumor cell-derived chemokines, while it activates eosinophils directly, up-regulating CD69, the adhesion molecules ICAM-1 and CD11b/CD18, and the degranulation marker CD63." (PMID 31717819, 2019). "We have also shown increased NK cell killing of target cells and increased expression of CD69 on NK cells from mouse TILs, suggesting a role for NK cells in the anti-tumor activity of MEDI9197, which warrants further investigation." (PMID 31511088, 2019). "Further, on day 10 of combination treatment, the number of activated (CD8+ CD69+) T cells in the tumor were increased and T-cell functions were enhanced, with an up-regulated expression of the effector T-cell markers, IFN-γ, Granzyme B, and KLRG1." (PMID 31781498, 2019). "Coincidently, in the current study, we found a similar T‐cell reaction induced by LDR, including upregulation of CD69 molecules in T cells, increased cytotoxicity of mouse splenocytes, and increased infiltration of T cells in the tumor tissues." (PMID 29479834, 2018).
tumor (continued). "This treatment not only enhance the tumor cell killing, but also the activation of γδ T cells as seen by augmented CD69, CD25, IFNγ, and TNFα expression." (PMID 30038626, 2018). "In contrast, another group claimed that sorafenib reduces the number and cytotoxicity of NK cells against tumor cells in tumor-bearing mice through downregulation of CD69 on the surface of NK cells, which needs further validation." (PMID 30463262, 2018). "The expression levels of CD80, CD86, and CD69 in B220+ B cells from splenocytes of HHT-treated mice were higher than that of control mice in two mouse tumor models." (PMID 29844447, 2018). "We also found that compared with the data for days 12 and 14, LDR‐induced antitumor immunity decreased on day 20 and thereafter, particularly for killing assays and CD69+ NK cell and T‐cell percentages, although total survival and tumor growth were improved." (PMID 29479834, 2018). "T lymphocytes expressing MζBB CARs displayed a high level of CD69 expression while in contact with cognate tumor cells, whereas sdCAR described here required an additional switch molecule for high expression of CD69, allowing for control of T cell activity." (PMID 29558951, 2018). "This includes the execution of the cytotoxic activity to kill infected or tumor cells, up-regulation of CD69 and CD25, as well as secretion of cytokines." (PMID 30038626, 2018). "In a B16-F10 mouse melanoma transplantable tumor model, a fraction of antigen-specific tumor-infiltrating CD8 T cells acquired CD69 and CD103 expression 3 weeks after tumor engraftment." (PMID 30298068, 2018). "When EnAd-infected tumor cells were incubated with DCs and T cells, the T cells showed a high level of activation as measured by production of IL-2, gamma-interferon, and CD69." (PMID 28345021, 2017). "As it happened for CD137 expression, the upregulation of CD69 on NK cells was significantly lower when nimotuzumab-bound tumor cells was used in comparison with cetuximab-activated NK cells." (PMID 28674498, 2017). "Following 20 days of B16-OVA tumour development, OT-I cells with a Trm cell-like phenotype, with most OT-I T cells expressing CD69 and 50% of them co-expressing CD103, were found in the tumour mass." (PMID 28714465, 2017). "Our flow cytometry and IHC results indicate a significant increase in CD69+CD4+ cells in the tumor cell areas." (PMID 27999289, 2016). "FACS results confirmed the activated state of FcγRIIlow/− B cells as following: most FcγRIIlow/− B cells from HCC tumours displayed a CD69+BTLA− activated phenotype with reduced B-cell follicle homing molecules CD62L, CXCR5 and CCR6." (PMID 27853178, 2016). "CD69+ cells were present at higher numbers in the tumor cell areas as compared to outside the tumor cell areas." (PMID 27999289, 2016). "We also compared CD69 surface levels and bendamustine response of tumor lymphocytes derived from the three typical anatomic CLL compartments: peripheral blood (PB), BM and LN." (PMID 26701728, 2016). "Supernatants from STAT3-targeted tumor cells increased the expression of NK activation markers, such as CD69, NKG2D, Fas ligand, granzyme B, perforin, and IFN-γ." (PMID 27148255, 2016). "The increased percentages of TEM and PD-1+CD4+ cells in NLPHL, combined with the increased numbers of CD69+ cells in the tumor cell area, suggests that egress of these cells from the tumor cell area is inhibited." (PMID 27999289, 2016). "Vice versa, loss of CD69+ cells and thus loss of TGF-β production can result in enhanced anti-tumor responses." (PMID 27999289, 2016). "Peripheral and tumor-associated NK cells from STAT3-targeted tumor-bearing mice also expressed elevated levels of NK activation markers NKG2D, CD69, and Fas ligand (FasL)." (PMID 27148255, 2016). "In contrast, almost all E7-DEX+ CD8+ T cells were CD69 positive in all tested tumour locations, with a large fraction of CD69+ CD49a+ cells in the subcutaneous model." (PMID 26931556, 2016).
tumor (continued). "CD69+ cells were increased in the tumor cell area in CD4+ and CD8+ T-cells, while FoxP3+CD25+CD4+ Tregs and CD25+CD8+ T-cells were significantly increased outside the tumor area." (PMID 27999289, 2016). "Instead, our observations highlight increased proliferation of highly suppressive CD69+ Tregs as a mechanism by which Tregs exert dominance within the tumor microenvironment." (PMID 26433463, 2015). "CD4+ CD25lo Tconvs were sorted from lymphoid tissue and co-cultured in the presence of anti-CD3 and anti-CD28 beads with either CD69+ or CD69− Tregs sorted from tumor draining or non tumor draining lymph nodes, at varying Tconv : Treg ratios." (PMID 26433463, 2015). "This ecto-CRT becomes an additional “eat me” signal and binds to CD91 and CD69 on dendritic cells to promote phagocytosis, facilitating their tumor antigen presentation and incitement of tumor antigen-specific cytotoxic T-cells." (PMID 26231031, 2015). "We found that si-A20 treated group showed a significant increase in CD8+ T cells and activated CD69+ CD8+ T cells in tumor tissues." (PMID 26561336, 2015). "These highly significant differences in CD69 expression between Tregs and Tconvs within both types of tumor is most striking when analysed by Mean Fluorescence Intensity (MFI) measurement." (PMID 26433463, 2015). "We describe that IL-15 increases NK1.1+ and CD69+ cell infiltration in tumour area and that NK cell depletion reduces the efficacy of IL-15 administration on tumour growth and of EE on tumour growth and mice survival." (PMID 25818172, 2015). "Compared to baseline, there was increased tumor infiltration following ipilimumab by fully activated (CD69+) CD3+/CD4+ T cells (mean change = 19; SD = 14, p = 0.06) and CD3+/CD8+ T cells (mean change = 11; SD = 19; p = 0.2)." (PMID 24498358, 2014). "(iii) Id-specific CD4+ tumor-infiltrating lymphocytes (TIL) were activated (CD69+ CD25+), and proliferated (BrdU+) in clusters associated with MHC IIPOS tumor-infiltrating APC." (PMID 24782871, 2014). "The expression of CD25 and CD69, which are molecules expressed on regulatory and activated T cells, was also increased in the tumor tissues compared to the normal colon tissues and the cultured CT26 cells." (PMID 25365349, 2014). "Ipilimumab induced increased tumor infiltration by fully activated (CD69+) CD3+/CD4+ and CD3+/CD8+ T cells with evidence of induction/potentiation of memory T cells (CD45RO+)." (PMID 24498358, 2014). "GRB2 interaction with SHC1 (pY439 and pY427) has been shown in T cells to induce Ras-Erk signaling and CD69 leading to tumor cell survival and promoting tumor vascularization." (PMID 23826330, 2013). "In contrast, we observed a significant decrease of CD69+/CD25+ CD8+ T cells in tumor-draining lymph nodes (tdLN) of high tumor-burdened LLA-TG-3 mice compared to low tumor-burdened LLA-TG-3 mice in PMA-supplemented medium (p < 0.005; Mann–Whitney U test)." (PMID 22674057, 2012). "Recently activated CD69+ T cells were relatively frequent in the unaffected lamina propria, but present in significantly lower numbers in the tumor." (PMID 22319577, 2012). "In contrast, we found a significantly reduced expression of the activation marker CD69 on PI3Kδ−/− tumor-infiltrating CTLs." (PMID 22808277, 2012). "Even more in contrast, our group proposed a negative regulatory role for CD69, since tumor-bearing CD69−/− mice showed increased anti-tumor immunity to NK sensible tumors." (PMID 23119065, 2012). "Our results showed that FoxP3+ Tregs highly aggregated and were in an activated phenotype (CD69+HLA-DRhigh) in the tumor site, where they can suppress the proliferation and INF-γ secretion of CD4+CD25− T cells." (PMID 21935436, 2011). "A previous study has indicated that CD4+CD69+CD25− cells represented a new subset of regulatory T cells in the tumor model." (PMID 21887301, 2011). "Following culture in reoTCM, NK cells upregulated CD69 expression and acquired greater lytic potential against tumour targets." (PMID 21338484, 2011).
tumor (continued). "Tumor cell-stimulated CD8+ CTLs exhibited a greater degree of CD25 activation but a lesser degree of CD69 activation compared to CD3-stimulated CTLs." (PMID 21124930, 2010). "For instance, it was demonstrated that CD69-/- mice display greatly prolonged tumor survival that was related to a decreased production of TGFβ." (PMID 19543397, 2009). "Combining CIR-mediated activation with FACS sorting of CD69+ T cells it is possible to detect and purify tumor-specific T cells with an enrichment factor of at least 103-fold after two rounds." (PMID 19777065, 2009). "TILs displayed an activated CD69+ phenotype, similar to SN lymphocytes, but when tested against autologous tumour antigens or Con A they did not proliferate." (PMID 16641897, 2006). "Furthermore, increased expression of SIGLEC15 was associated with higher levels of PD-1, FOXP3 and, CXCR1, and lower levels of CD69 in tumor tissues." (PMID 41158758, 2026). "Furthermore, tasquinimod treatment alone or combined with cisplatin significantly enhanced tumor infiltration of activated CD8+ (CD69-positive) T cells." (PMID 41173834, 2025). "Moreover, the proportion of NKG2A+ cells was significantly higher in tumor infiltrating CD8+ T cells also expressing CD69+ or GZB+ as well as in CD69+ CD4+ Tconv cells." (PMID 39706891, 2025). "After primary tumor excision and vitiligo induction, tumor‐specific CD69+CD103+ TRM persist for months in RLNs; parabiosis and rechallenge experiments show these cells neither recirculate nor rely on circulating memory T cells, yet their presence alone prevents metastatic seeding in the LN." (PMID 41361844, 2025). "Furthermore, H-151 not only inhibited the p-STING/p-IRF3 axis but also significantly reduced the expression of T cell infiltration and activation markers (CD3D and CD69) as well as anti-tumor factors (GZMB, IFNγ, and TNFα)." (PMID 40846839, 2025). "Indeed, we observed that the preferential expression of CD49a and CD69 correlated with the ability of NK cells to infiltrate the tumor via CXCR3." (PMID 40168086, 2025). "Additionally, fewer effector CD8+ T cells and increased LGALS1-CXCR4/CD69 and TGFB1-CXCR4 interactions between tumor cells and other TMEs are linked to ibrutinib resistance." (PMID 40876452, 2025). "As expected, the CD8+CD69+ T cells from PanNV plus αMSLN treated group exhibited nearly eight times of the tumor‐killing efficiency compared to those from the PBS and αMSLN treated groups, and nearly two times of the tumor‐killing efficiency compared to the PancNV treated group (p < 0.0001)." (PMID 39887656, 2025). "Tumor-infiltrated γδT cells showed significantly increased proportions expressing CD69 and PD-L1." (PMID 41221283, 2025). "In addition, CD8+ T cells demonstrated significantly higher proportions expressing the activation marker CD69+ in the tumor tissues (18.03 ± 4.17% of CD8+ T cells) compared to PB (3.14 ± 1.43% of CD8+ T cells)." (PMID 41221283, 2025). "Interestingly, upregulation of both CD69 and PD-1 was observed on tumor-infiltrating CD8+ T cells following both beta-emitting and alpha-emitting radiotherapies, in contrast to untreated tumors." (PMID 40475779, 2025). "By using flow cytometry, we could dive further into the activation status of T cells, thereby detecting increased expression of CD39, CD69, and programmed cell death protein 1 (PD-1) in the tumor, whereas CD127 expression was reduced." (PMID 39918475, 2025). "Furthermore, significant positive correlations between blood-circulating and tumor-infiltrated NKp46+ NK cells were found in our cohort, while CD69+ NK cells correlated significantly positive between ascites and tumor." (PMID 41221283, 2025). "Accordingly, our results demonstrate that the CD103+CD69+ lymphocyte population (Trm cells) is widely present at the tumor level, and, in contrast to what we would expect, even double‐positive or single PD‐1+ subpopulations have a very high percentage of proinflammatory cytokine production." (PMID 40498413, 2025).